GIMAP5 (GTPase, IMAP family member 5)
Diseases named in the same sentence as GIMAP5 in open-access papers (continued):
Sharing a sentence is not in itself a finding about the gene and the disease.
lung carcinoma (6 papers, 2020 to 2025). "Previous studies on GIMAP5 have shown that that its low expression is associated with poor prognosis in lung cancer." (PMID 40873572, 2025). "Five of the seven genes (BIRC5, GIMAP5, HBB, IL33, and AKAP12) associated with the LC-LK alignments have been observed to be deregulated in lung cancer." (PMID 36101460, 2022). "To explore the biological function of Gimap5 in lung cancer progression, we constructed Gimap5-overexpressed cell lines for PC9, A549 and 1299 cells." (PMID 34604035, 2021). "In the scratch migration experiment, we found that Gimap5 overexpression significantly decreased the proliferation and migration abilities of lung cancer cell lines compared with those in the control group." (PMID 34604035, 2021). "As PADI4 is a positive regulator of EMT, we further clarified the role of Gimap5 in inhibiting lung cancer via EMT downregulation." (PMID 34604035, 2021). "Experimental results revealed that the expression levels of GIMAP5 in all lung cancer cell lines were lower than those in Beas-2b cells." (PMID 34604035, 2021). "The survival analysis of the GIMAP family was performed, and the results showed that high levels of GIMAP1, GIMAP2, GIMAP4, GIMAP5, GIMAP, GIMAP7 and GIMAP8 mRNA expression levels were associated with better overall survival of patients with lung cancer." (PMID 34604035, 2021). "In this study, we conducted a preliminary study on the mechanism of Gimap5 in lung cancer progression." (PMID 34604035, 2021). "After the survival rates of the cells were analyzed, we constructed Gimap5 over-expressed lung cancer cell lines and assessed the effects of Gimap5 on cell migration, cell invasion, cell proliferation and the epithelial-mesenchymal transition (EMT)." (PMID 34604035, 2021). "The expression of GIMAP5 in various lung cancer cell lines was detected using qRT-PCR, such as PC9, A549 and 1299 and normal human bronchial epithelial cells (Beas-2b)." (PMID 34604035, 2021). "To further verify the ability of Gimap5 to regulate lung cancer metastasis, we studied the effect of Gimap5 on the expression levels of EMT biomarkers (E-cadherin, N-cadherin, Snail, Slug, Twist, ZO-1, Vimentin) in PC9, A549 and 1299 cells." (PMID 34604035, 2021). "All in all, in this study, we found that the expression of Gimap5 in lung cancer cells and tissues decreased considerably and that the low expression of Gimap5 predicted the poor clinical prognosis of lung cancer patients." (PMID 34604035, 2021). "After assessing the effect of Gimap5 on lung cancer invasion and migration in vitro using Transwell analysis, we found that the invasion abilities of cells with Gimap5 overexpression were significantly downregulated and that they decreased by 60% compared with the control group." (PMID 34604035, 2021). "However, the mechanisms through which Gimap5 regulates lung cancer cells are yet to be thoroughly investigated in the literature." (PMID 34604035, 2021). "Our study aimed to investigate the function of Gimap5 in the development of lung cancer." (PMID 34604035, 2021). "Therefore, the main purpose of this study is to explore the role of Gimap5 in the occurrence and development of lung cancer." (PMID 34604035, 2021). "Overall, our research suggested that Gimap5 could inhibit the growth of lung cancer by interacting with M6PR and that it could be a potential biomarker for the diagnosis and prognosis of lung cancer." (PMID 34604035, 2021). "Our results showed that the expression of Gimap5 was low in lung cancer tissues and cells." (PMID 34604035, 2021). "In short, our finding suggested that Gimap5 might be used as a biomarker for the diagnosis and prognosis of lung cancer." (PMID 34604035, 2021). "In sum, these data indicated that GIMAP5 was downregulated in lung cancer." (PMID 34604035, 2021). "This enhancement suggested that Gimap5 could be a therapeutic target for lung cancer." (PMID 34604035, 2021).
lung carcinoma (continued). "Findings also revealed that Gimap5 inhibited the invasion, migration, proliferation and EMT of lung cancer cells." (PMID 34604035, 2021). "Our experimental results showed that Gimap5 could inhibit the migration, invasion, proliferation and EMT of lung cancer cell lines." (PMID 34604035, 2021). "This outcome suggested that Gimap5 promoted the transfer of M6PR to the cell membrane and might inhibit the growth of lung cancer cells via the processing of M6P modified ligands." (PMID 34604035, 2021). "Our research suggested that Gimap5 could inhibit the growth of lung cancer by interacting with M6PR and that it could be a potential biomarker for the diagnosis and prognosis of lung cancer." (PMID 34604035, 2021). "We employed machine learning algorithms to screen six genes, BATF, CXCR3, GIMAP5, GPR8, IGHM, and ISG20, that have been extensively investigated in other cancers, including lymphoma, melanoma, leukemia, breast cancer, multiple myeloma, hepatocellular carcinoma, and lung cancer." (PMID 39559348, 2024). "Therefore, we believed that Gimap5 might play a role in the degradation of M6P modified ligands (i.e., PADI4) via M6PR, thereby inhibiting the growth of lung cancer." (PMID 34604035, 2021).
asthma (3 papers, 2021 to 2025). "GIMAP4 was associated with allergic sensitization, while GIMAP5 was linked to asthma." (PMID 41042382, 2025). "Interestingly, the authors found that a particular GIMAP5 SNP (rs6965571) was associated with increased risk for both asthma and allergic sensitization but was inversely associated with T1DM." (PMID 34071190, 2021).
Autoimmunity (3 papers, 2017 to 2025). The occurrence of an immune reaction against the organism's own cells or tissues. "GTPase of immunity-associated protein 5 (Gimap5) is linked with lymphocyte survival, autoimmunity, and colitis, but its mechanisms of action are unclear." (PMID 29382851, 2018).
breast carcinoma (3 papers, 2024 to 2025). "Another bioinformatic analysis on GIMAP family members indicated that GIMAP7 together with GIMAP1, GIMAP5, GIMAP6, and GIMAP8, are lowly expressed in breast cancer tissues." (PMID 38151913, 2024). "Bioinformatics show GIMAP1, GIMAP5, GIMAP6, GIMAP7, and GIMAP8 are downregulated in breast cancer." (PMID 40535419, 2025).
colitis (3 papers, 2014 to 2018). Inflammation of the colon. "Here, we discuss these critical aspects in the context of human IBD and consider the mechanistic pathways by which loss of Gimap5 leads to a loss of immunological tolerance ultimately causing the development of early-onset and severe colitis." (PMID 25944983, 2015). "In this review, we summarize recent findings derived from studies involving a novel early-onset model of colitis as it develops in GTPase of immunity-associated protein 5- (Gimap5-) deficient mice." (PMID 25944983, 2015). "Gimap5sph/sph mice, an ENU germline mutant with a missense mutation in Gimap5, showed a progressive loss of the peripheral lymphocyte populations and developed spontaneous colitis, resulting in early mortality." (PMID 25038616, 2014). "Importantly, we show that pharmacological targeting of GSK3 or genetic deletion of Gsk3b corrects T lymphocyte survival and prevents severe early-onset colitis in Gimap5-deficient mice." (PMID 29382851, 2018). "Here, we discuss how defects in Gimap5 function impair immunological tolerance and lymphocyte survival and ultimately drive the development of CD4+ T cell-mediated early-onset colitis." (PMID 25944983, 2015).
hepatocellular carcinoma (3 papers, 2020 to 2024). A malignant tumor that arises from hepatocytes. "It was reported that the downregulation of the mRNA and protein expression levels of GIMAP5 and GIMAP6 in the tumor tissues and blood of patients with hepatocellular carcinoma." (PMID 33115964, 2020). "That suggested GIMAP5 and GIMAP6 could involve in the pathogenesis of hepatocellular carcinoma." (PMID 33115964, 2020).
COVID-19 (2 papers, 2025). A disease caused by infection with severe acute respiratory syndrome coronavirus 2. "The hypermethylated genes with lowest p-values for hospitalized COVID-19 patients at inclusion (T1) and at 6 weeks post-inclusion (T2) versus HCs included NXN, SLC2A12, RAD54L2, GIMAP5, and PPP2R5C, while the top five hypomethylated genes with lowest p-value were, LOC101928650, DLX5." (PMID 41227320, 2025).
Immunodeficiency (2 papers, 2015 to 2018). Failure of the immune system to protect the body adequately from infection, due to the absence or insufficiency of some component process or substance. "We show that a dysregulation of GSK3 in lymphocytes can lead to a primary immune deficiency, as observed in Gimap5sph/sph mice and the GIMAP5 LOF patient." (PMID 29382851, 2018). "Such a severe immunodeficiency would be predicted to present in infancy as a monogenic trait and, with the current sequencing capacity and efforts, de novo mutations in GIMAP5 should be considered prime causal candidates." (PMID 25944983, 2015). "Finally, given the severe phenotypes related to the host immune system observed in both mouse and rat Gimap5-deficient models, a GIMAP5 null phenotype in humans is expected to result in a severe immunodeficiency, although the phenotype has yet to be described." (PMID 25944983, 2015).
T cell deficiency (2 papers, 2018 to 2025). "To define the T cell deficiency in the GIMAP5−/− patient, we compared T cell proliferation from the patient with his heterozygous mother." (PMID 29382851, 2018).
airway hyperresponsiveness (1 paper, 2019). "Loss of Gimap5 promoted pathogenic Th2 and Th17 cells in humans and mice and led to an exacerbated lung allergic inflammation and airway hyperresponsiveness in mice, and Gimap5 is implicated in regulating CHOP activity." (PMID 30978945, 2019).
anaplastic large cell lymphoma (1 paper, 2021). Anaplastic large cell lymphoma (ALCL) is a rare and aggressive peripheral T-cell non-Hodgkin lymphoma, belonging to the group of CD30-positive lymphoproliferative disorders, which affects lymph nodes and extranodal sites. "The expression of GIMAP5 occurs in many T cell leukemic cell lines and in anaplastic large cell lymphoma (ALCL) cell lines while the expression of GIMAP1, GIMAP2, GIMAP6 and GIMAP7 were down-regulated in ALCLs." (PMID 34135906, 2021).
leukemia (1 paper, 2024). A malignant (clonal) hematologic disorder, involving hematopoietic stem cells and characterized by the presence of primitive or atypical myeloid or lymphoid cells in the bone marrow and the blood. "GIMAP5 has been linked to the survival and homeostasis of lymphocytes and may influence the clinical outcome in leukemia." (PMID 39559348, 2024).
neuroblastoma (1 paper, 2024). Neuroblastoma (NB) is the most common solid, extracranial childhood tumor. "Six characteristic genes (BATF, CXCR3, GIMAP5, GPR18, ISG20, and IGHM) were identified by machine learning, and these genes are associated with multiple immune-related pathways and immune cells in neuroblastoma." (PMID 39559348, 2024). "BATF, CXCR3, GIMAP5, GPR18, IGHM have lower expression in high-risk neuroblastoma patients." (PMID 39559348, 2024). "BATF, CXCR3, GIMAP5, GPR18, ISG20, and IGHM may serve as biomarkers that reflect the conditions of the immune microenvironment of neuroblastoma and hold promise in guiding neuroblastoma treatment." (PMID 39559348, 2024).
Sepsis (1 paper, 2025). Sepsis is defined as life-threatening organ dysfunction caused by a dysregulated host response to infection. "Downregulated genes in sepsis Th2 cells were significantly overrepresented in processes related to viral responses (including TNFRSF25 and GIMAP5; -0.79 and -0.49log2FC, respectively) and differentiation (ZAP70; -0.66log2FC)." (PMID 41208955, 2025).
tumor (7 papers, 2016 to 2025). "GIMAP5 (GTPase IMAP Family Member 5), another high scoring LUAD gene (11th), is consistently repressed in paired analyses of tumor vs normal lung tissue from the same patient, and encodes an anti-apoptotic protein." (PMID 27145341, 2016). "GIMAP5 might regulate T cell development and function within the tumor microenvironment, possibly affecting the survival and function of immune cells and the overall immune response against NBL cells." (PMID 39559348, 2024). "Current studies have revealed the role of GIMAP5 in tumor inhibition." (PMID 34604035, 2021). "Our follow-up study also showed that the function of Gimap5 depended on its interacting protein M6PR, a tumor suppressor gene." (PMID 34604035, 2021).
cancer (4 papers, 2009 to 2024). A tumor composed of atypical neoplastic, often pleomorphic cells that invade other tissues. "By analyzing the immune landscape of NBL, we identified six genes - BATF, CXCR3, GIMAP5, GPR8, IGHM, and ISG20-with diagnostic and clinical significance in other cancers, but whose roles in NBL remain largely unexplored." (PMID 39559348, 2024). "Down-regulation of GIMAP5 in lung tumors therefore potentially facilitates their evasion of programmed cell death, one of the hallmarks of cancer." (PMID 27145341, 2016). "Of the novel Notch target genes so far analysed at the mRNA level, we chose to focus on VEGF, ID1, and GIMAP5 because of their known involvement in cancer or T cell development." (PMID 19508709, 2009). "Besides, we found that Gimap5 overexpression inhibited cell proliferation but promoted the apoptosis of all three cancer cell lines." (PMID 34604035, 2021).
immune disease (3 papers, 2015 to 2025). "GTPase of immunity-associated protein 5 (Gimap5) is linked with lymphocyte survival, immune homeostasis, and (auto)immune disease." (PMID 29382851, 2018). "GIMAP5 is essential for T cell survival and homeostasis; its deficiency leads to impaired maturation and survival of CD4+ and CD8+ T cells, as well as defective NK and NKT cell development, and is associated with immune dysfunction and liver pathology in both rodents and humans." (PMID 41042382, 2025).
infection (2 papers, 2019 to 2021). The state of being infected such as from the introduction of a foreign agent such as serum, vaccine, antigenic substance or organism. "The GO analysis showed that Gimap5 promoted the function of anti-infection, cytoplasmic vesicle lumen, secretory granule lumen and lysosome." (PMID 34604035, 2021).
GIMAP5 also shares sentences with these, for which no sentence is quoted: melanoma (2 papers); Crohn disease (1); Hypertension (1); lung adenocarcinoma (1); lymphoma (1); multiple myeloma (1).